CCL4 (C-C motif chemokine ligand 4)
Diseases named in the same sentence as CCL4 in open-access papers (continued):
Sharing a sentence is not in itself a finding about the gene and the disease.
metabolic syndrome (5 papers, 2014 to 2023). A cluster of metabolic risk factors for CARDIOVASCULAR DISEASES and TYPE 2 DIABETES MELLITUS. "The insulin concentrations in the CCL4 inhibition group were increased at 15 minutes but were significantly lower at 30 minutes compared to those in the untreated metabolic syndrome group during the OGTT." (PMID 33968046, 2021). "The blood sugar levels were lower in the CCL4 antibody-treated group at 30, 60, 90 and 120 minutes than in the untreated metabolic syndrome group." (PMID 33968046, 2021). "In metabolic syndrome mice, the CCL4 inhibition group had lower levels of HOMA-IR than the IgG control group (CCL4 inhibition for 4 weeks group (89.33 ± 11.41) vs. DM+IgG group (161.17 ± 14.52), P<0.01)." (PMID 33968046, 2021). "Furthermore, the TNF-α and IL-6 levels were decreased in the CCL4 antibody-treated group compared with those in the IgG-treated metabolic syndrome group." (PMID 33968046, 2021). "Furthermore, systemic inflammation, indicated by serum TNF-α and IL-6 levels, was also decreased by CCL4 inhibition in type 2 DM and metabolic syndrome mouse models in this study." (PMID 33968046, 2021). "In addition, mice receiving the CCL4 antibody showed lower serum insulin levels, higher insulin-positive areas and more intact with large pancreatic volume and closely arranged pancreatic β-cells morphology than the IgG-treated metabolic syndrome mice." (PMID 33968046, 2021). "Second, treatment with the CCL4 antibody could retard the elevation of blood sugar levels in db/db mice (a model simulating type 2 DM) and reduce the blood sugar levels in mice fed a high fat diet (a model simulating metabolic syndrome)." (PMID 33968046, 2021). "Therefore, it is possible to envisage that CCL4 may act as a possible node to link the presence of metabolic syndrome to psoriasis." (PMID 34006909, 2021). "CCL4 inhibition mice also had decreased levels of phosphorylated IRS-1 in both skeletal muscle and liver tissues compared to those in the untreated metabolic syndrome mice, implying the beneficial effects of CCL4 inhibition on insulin signaling." (PMID 33968046, 2021). "CCL4, also known as MIP-1β, is expressed at two-fold higher levels in obese and metabolic syndrome subjects compared with those in healthy individuals." (PMID 27869712, 2016). "In this study, we revealed for the first time that direct inhibition of CCL4 could reverse the impaired insulin signaling pathway by decreasing the phosphorylation of IRS-1 in skeletal muscle and liver tissues in mice with both type 2 DM and metabolic syndrome." (PMID 33968046, 2021).
nasal polyps (5 papers, 2020 to 2025). "The epithelial cells of nasal polyps with high eosinophil count (>100/HPF) indicated a lower intensity of MUC1-FL with higher intensity of CCL4 than those with low eosinophils (<100/HPF)." (PMID 39791734, 2024). "CCL4 expression was positively correlated with the eosinophil count in nasal polyps (HPF), which agrees with a previous report." (PMID 39791734, 2024). "First, CCL4 expression in nasal polyps from patients with ECRS as well as its role of CCL4 in eosinophilic airway inflammation were investigated in an in vivo model." (PMID 36555793, 2022). "Four months after treatment with dupilumab, an IL-4 receptor-α antagonist, CCL4 expression in nasal polyps was significantly reduced." (PMID 35892679, 2022). "CCL4 was mainly located in nasal polyp epithelial cells, while serum CCL4 levels were reduced after dupilumab treatment." (PMID 35892679, 2022). "The present study demonstrated that CCL4 was released by epithelial cells, and it was significantly increased in eosinophil-rich nasal polyps from patients with ECRS; moreover, epithelial cell-induced CCL4 was correlated to the number of infiltrated eosinophils." (PMID 36555793, 2022). "While dupilumab reduced CCL4 expression in nasal polyps, its mechanism was unclear." (PMID 35892679, 2022). "However, compared with the other chemoattractants in this study, CCL4 was significantly increased in eosinophil-rich nasal polyps and was expressed in bronchial epithelial cells coincubated with eosinophils." (PMID 36555793, 2022). "Therefore, CCL4 in mucin might be involved in the shedding of the MUC1 N-terminal domain; accordingly, the association between CCL4 and MUC1 expression in the nasal polyps of patients with CRSwNP was examined." (PMID 39791734, 2024). "The expression of CCL4 and other eosinophilic chemoattractants (CCL5, CCL11, and CCL26) was reported to be increased in nasal polyps compared with that in uncinate process tissues of the same patients with ECRS." (PMID 36555793, 2022). "Recently, CCL4, CCL5, CCL11, and CCL26 expressions were found to be higher in nasal polyps than in uncinate process tissue in the same patients with ECRS." (PMID 36555793, 2022). "The eosinophilic chemo-attractants CCL4, CCL5, CCL11, and CCL26 were increased in nasal polyps compared with uncinate process tissues." (PMID 32085629, 2020). "Notably, mRNA expression of CCL4, but not other well-known eosinophil-associated chemokines, such as CCL5, CCL11, and CCL26, was significantly higher in nasal polyps of patients with ECRS than in uncinate tissues of the same patients." (PMID 36555793, 2022). "Notably, CCL4 expression, but not CCL5, CCL11, or CCL26, was found to be significantly increased in nasal polyps from patients with ECRS associated with eosinophil infiltration as well as in BEAS-2B cells co-incubated with eosinophils." (PMID 36555793, 2022).
non-alcoholic fatty liver disease (5 papers, 2019 to 2024). "Tea and its extracts confer protective effects against alcoholic liver disease, non-alcoholic fatty liver disease, CCL4-induced liver injury, and inflammatory liver damage." (PMID 38420363, 2024). "Moreover, a recent systematic review and meta-analysis suggested that chemokines, CCL3, CCL4, CCL5, CCL20, CXCL8 and CXCL11, are implicated in the pathogenesis of non-alcoholic fatty liver disease, post-traumatic stress disorder, and also different types of cancers." (PMID 34054797, 2021). "Moreover, a recent systematic review and meta-analysis suggested that the chemokines, CCL3, CCL4, CCL5, CCL20, CXCL8 and CXCL11, are implicated in the pathogenesis of non-alcoholic fatty liver disease, post-traumatic stress disorder, and also different types of cancers." (PMID 35242125, 2021).
periodontitis (5 papers, 2018 to 2023). An acute or chronic inflammatory process that affects the tissues that surround and support the teeth. "By comparing differentially expressed genes in neutrophils between the two groups, several inflammation‐associated genes, such as IL1B, CD44, CXCL8, and CCL4 were upregulated in the gingivae from patients with periodontitis versus healthy subjects." (PMID 37639212, 2023). "Our scRNA-seq analysis revealed that macrophages expressed Ccl2, Ccl9, Cxcl4, and Cxcl6, and neutrophils expressed Ccl3, Ccl4, Ccl6, Cxcl2, and Cxcl3 throughout periodontitis development." (PMID 38015204, 2023).
schizophrenia (5 papers, 2019 to 2025). A major psychotic disorder characterized by abnormalities in the perception or expression of reality. "The absence of a positive correlation between the medication at the time of blood drawing and RGS1/CCL4 argues against an interpretation that the decreased levels of RGS1/CCL4 could be caused by psychotropic medication of the schizophrenia patients." (PMID 31150013, 2019). "In contrast, CCL4 levels may be increased in other neuro-psychiatric disorders such as schizophrenia." (PMID 34755124, 2021). "Interestingly, a recent meta-analysis also identified significantly decreased CCL4 gene expression in schizophrenia patients, as well as other modulated genes from the same correlated network, but not RGS153." (PMID 31150013, 2019). "While more studies are needed to characterize the RGS1/CCL4-defined schizophrenia subset and its clinical relevance, our here-proposed approach may prove valuable for changing the diagnostic culture in clinical psychiatry." (PMID 31150013, 2019). "At this point, it is unclear whether in the schizophrenia patients investigated here, CCL4 expression is decreased in PBMCs or whether specific PBMC subpopulations accountable for its expression are decreased in number." (PMID 31150013, 2019). "In the hypothesis-guided analysis presented here, however, a causal model, the tgDISC1 rat, was used to define aberrant PBMC signaling that was then rediscovered in a schizophrenia subset converging on the marker combination CCL4/RGS1." (PMID 31150013, 2019). "Besides, the most reliable data confirmed by the results of meta-analyses showed an increase in CXCL8/IL-8, CCL2/MCP-1, CCL4/MIP-1β, CCL11/eotaxin-1 in the blood of patients with schizophrenia." (PMID 36768537, 2023). "We propose to apply testing for RGS1/CCL4 in many more cases of chronic mental illness, not limited to schizophrenia, but also to include recurrent affective disorders and neurological brain diseases to delineate its diagnostic accuracy." (PMID 31150013, 2019).
acute liver failure (4 papers, 2019 to 2024). Rapid deterioration of liver function causing encephalopathy and coagulopathy. "However, in the current investigation, we demonstrated the therapeutic benefit of tadalafil in rats with acute liver failure caused by CCL4, particularly when combined with L. sativum extract, which showed a more significant therapeutic effect." (PMID 38413963, 2024). "MSC therapy efficiently prolonged the survival time of CCL4 induced acute liver failure mice from day 2 to day 7 after transplantations of second trimester amniotic fluid (AF-MSCs), and the ALT and AST levels significantly decreased by 35.36% and 64.72%, respectively." (PMID 37744328, 2023). "CCL11 (Eotaxin) was selectively increased in biliary atresia patients, while IL-3, IL-6, CXCL8 (IL-8), IL-9, IL-16, MIF, CCL4 (MIP-1 β), and CXCL1 (GRO-α), were increased in both biliary atresia and acute liver failure." (PMID 30740106, 2019).
Allergy (4 papers, 2018 to 2022). An allergy is an immune response or reaction to substances that are usually not harmful. "In an OVA-induced allergy murine model, CCL4 increased eosinophil accumulation in the nasal mucosa and BALF." (PMID 36555793, 2022). "did provide a proof that acteoside could alleviate inflammatory response by down-regulating the expression of CCL1, CCL2, CCL3 and CCL4 in allergy." (PMID 29708439, 2018).
anemia (4 papers, 2015 to 2023). A reduction in the number of red blood cells, the amount of hemoglobin, and/or the volume of packed red blood cells. "CCL4 is known to cause hematological aberrations including lysis of RBCs and anemia following its metabolism and ROS production." (PMID 35342748, 2022). "The xenobiotics like CCL4 can induce eryptosis i.e. the destruction of aged and damaged red blood cells, causing increased degradation of RBCs from the systemic circulation and associated with the symptoms of anemia." (PMID 32307011, 2020). "On the other hand, the circulating levels of IL-1β, IL-8, CXCL10, IL-6, CCL4, IL-1RA and CCL2 displayed an inverse behavior, with rising levels being proportional to increases in anemia severity." (PMID 37143662, 2023). "Nampt/PBEF/visfatin expression in nontumor tissue, both mRNA and protein, increased in patients with metastatic disease and mild anemia, and, on transcriptional level, correlated with HIF1α, IL1β, IL8, CCL2, and CCL4 expression." (PMID 26075243, 2015).
breast tumors (4 papers, 2017 to 2020). "We have previously reported that breast tumors with a high content of CCL2 or CCL4 had a higher infiltration of B and T lymphocytes." (PMID 32727083, 2020).
coronary artery disease (4 papers, 2019 to 2024). "The same study reported both CCL4 and CCR5 levels to significantly reduce in response to a low‐dose statin treatment, of which the former's reduction has been reported by others as well, albeit in a cohort of patients with coronary artery disease." (PMID 36467791, 2022). "LPS-induced CCL4 production in human monocytes has a significant positive correlation with LDL and total cholesterol concentration in vitro, and increasing expression of CCL4 in peripheral blood of patients with coronary artery disease was reduced by statin therapy." (PMID 31449494, 2019).
cutaneous melanoma (4 papers, 2020 to 2022). A primary melanoma arising from atypical melanocytes in the skin. "Patients with high expression of CXCL9, CXCL10, CXCL13, CCL4, and CCL5 in SKCM (Skin cutaneous melanoma) had better overall survival." (PMID 36341437, 2022). "primarily identified five chemokine members (CCL4, CCL5, CXCL9, CXCL10, CXCL13) as relevant biomarkers in cutaneous melanoma tumorigenesis and progression." (PMID 36713580, 2022). "In summary, this study mainly identified five chemokine members (CXCL9, CXCL10, CXCL13, CCL4, CCL5) associated with SKCM tumorigenesis, progression, prognosis and immune infiltrations, which might help us evaluate several immune-related targets for cutaneous melanoma therapy." (PMID 32508531, 2020).
esophageal squamous cell carcinoma (4 papers, 2017 to 2023). Esophageal squamous cell carcinoma (ESCC) is a type of esophageal carcinoma (EC) that can affect any part of the esophagus, but is usually located in the upper or middle third. "Elevated expression of CCL4 in tumors was associated with unfavorable prognosis in renal carcinoma, but favorable prognosis when detected in colorectal, endometrial, and melanoma tumors and esophageal squamous cell carcinoma." (PMID 33202734, 2020). "For example, for esophageal squamous cell carcinoma patients, a high CCL4 level indicates prolonged survival." (PMID 37593100, 2023). "Inversely, an increase in the expression of ccl4 in esophageal SCC showed a significant correlation with a favorable prognosis." (PMID 35463731, 2022). "However, in patients with esophageal squamous cell carcinoma, the increased CCL4 expression may also improve the prognosis by altering the cancer microenvironment and recruiting CD8+ T cells to strengthen cancer immunity." (PMID 37593100, 2023). "Indeed, a study on esophageal squamous cell carcinoma showed that elevated tumor expression of CCL4 predicted prolonged survival, but a CCL4high/CCL20low group demonstrated better overall survival, whereas CCL4low/CCL20low and CCL4low/CCL20high groups showed the worst overall survival." (PMID 33202734, 2020). "Conversely highly level of CCL4 expression in esophageal squamous cell carcinoma (ESCC) was correlated with a more favorable prognosis, suggesting a role of CCL4 in recruitment of tumor infiltration CD8+ T lymphocytes and affect cancer microenvironment." (PMID 28404909, 2017).
Granuloma (4 papers, 2012 to 2025). A compact, organized collection of mature mononuclear phagocytes, which may be but is not necessarily accompanied by accessory features such as necrosis. "CXCL10 and CCL4 facilitate the migration of Th1 and CD8+ T cells to the granuloma (Soong, Henard and Melby, 2012), while CXCL9 recruits CD8+ T cells, Th1 cells, and NK cells, amplifying the immune response in granuloma areas." (PMID 40556761, 2025).
liver cancer (4 papers, 2015 to 2025). An epithelial or non-epithelial malignant neoplasm that arises from the liver. "In addition, scRNA-seq analysis of 124 liver cancer patients showed that CCL4+ TANs recruited macrophages through CCL4/CCR5 signaling, and depletion of neutrophils attenuated macrophage recruitment and suppressed T cell activity, thereby inhibiting tumor growth." (PMID 40453088, 2025).
neuropathy (4 papers, 2017 to 2023). A disorder affecting the nervous system that manifests with pain, tingling, numbness, and/or muscle weakness. "Similarly, studies conducted in streptozotocin- and chemotherapy-induced neuropathy models have suggested little, if any, participation of CCL4 in pathological nociception." (PMID 37570736, 2023). "A blockade of the CCL3-CCL4-CCL5/CCR5 axis with maraviroc, a CCR5 antagonist, also reduces NP symptoms by inhibiting the expression of CCL3, CCL4 and CCL5 and intensifies morphine and buprenorphine analgesia in the CCI neuropathy model." (PMID 35330149, 2022). "Clinical studies analyzing the levels of different chemokines in the body fluids of patients with NP have shown that neuropathy increases the concentration of CX3CL1, CXCL5, CXCL10, CCL8, or CCL11 in cerebrospinal fluid (CSF), CCL2, CCL3, CCL4, CCL19 in plasma, and CCL3, CCL4 in saliva." (PMID 35330149, 2022). "Furthermore, the serum cytokine profiles of CTS patients were readily distinguishable from those of controls with distinct patterns of the chemokines CCL2, CCL4, CCL5, CXCL8 and CXCL10 and the growth factors VEGF, PDGF and G-CSF, which may be induced by the neuropathy." (PMID 28811623, 2017). "Studies conducted in streptozotocin- and chemotherapy-induced neuropathy models have shown the participation of CCL4 in nociception; however, in contrast, its protein levels do not increase in CCI-evoked neuropathy." (PMID 36611891, 2022).
tuberculosis (4 papers, 2015 to 2024). A chronic, recurrent infection caused by the bacterium Mycobacterium tuberculosis. "CXCL10 has been used to distinguish between tuberculosis and latent tuberculosis, and a significant decrease in CCL4 expression was observed in individuals with latent tuberculosis after antituberculosis treatment associated with a decreased risk of developing active tuberculosis." (PMID 34722780, 2021).
ulcerative colitis (4 papers, 2009 to 2025). An inflammatory bowel disease involving the mucosal surface of the large intestine and rectum. "For instance, the up-regulated expression of chemokines, such as CCL2, CCL3, CCL4, CCL7, CCL8 and CXCL8 has been shown in mucosal biopsies from patients with CD and ulcerative colitis, and this up-regulation correlated with the disease activity." (PMID 19421322, 2009).
adenoma (3 papers, 2022 to 2024). A neoplasm arising from the epithelium. "In adenomas, only CCL4 was expressed at comparable level between the lesion and paired normal mucosa, while the expression of CCL3 (p = 0.006), CXCL2 (p = 0.023) and CCL19 (p = 0.016) was significantly higher in lesions." (PMID 38338661, 2024). "This notion is substantiated by CCL19 downregulation in adenomas with high-grade dysplasia and by an inverse association of CCL3 with polyp size and of CCL4 with number of polyps." (PMID 38338661, 2024). "Likewise, CCL19 and CCL4 proteins were significantly more abundant in hyperplastic polyps than adenomas." (PMID 38338661, 2024). "Hyperplastic polyps differed from adenomas with significantly higher CCL19 (p = 0.017) and CCL4 (p = 0.007) expression in lesions." (PMID 38338661, 2024). "The individual analysis of polyps with adenocarcinomas (AC) and precancerous lesions of classic adenoma (A) and alternative serrated (H) transformation pathways showed opposite trends in serrated (upregulation) and classic (downregulation) pathways, significant for CCL3 and non-significant for CCL4." (PMID 38338661, 2024).
Anxiety (3 papers, 2021 to 2025). Intense feelings of nervousness, tension, or panic often arise in response to interpersonal stresses. "Our findings revealed significant upregulation of chemokines Ccl3, Ccl4, Ccl5 and the inflammatory mediator Cd86 in Asm KO-induced anxiety." (PMID 39905541, 2025). "The early onset TSD mouse model Hexa−/−Neu3−/− mice demonstrated a high level of anxiety, along with elevated levels of Ccl2, Ccl3, Ccl4, Cxcl10." (PMID 39905541, 2025). "Positive correlations were observed between MIP-1α/CCL3, MIP-1β/CCL4, MCP-1/CCL2, MIP-3α/CCL20, RANTES/CCL5, Eotaxin/CCL11, and I-TAC/CXCL11 with high scores for anxiety (HARS) (p < 0.05) and for depression (HDRS) (p < 0.004)." (PMID 34863117, 2021).